LRG1 (leucine rich alpha-2-glycoprotein 1)
Diseases named in the same sentence as LRG1 in open-access papers (continued):
Sharing a sentence is not in itself a finding about the gene and the disease.
atherosclerosis (8 papers, 2017 to 2026). A disease characterized by the build-up of fatty material and calcium deposition in the arterial wall resulting in partial or complete occlusion of the arterial lumen. "To further explore the association between LRG1 and atherosclerosis, we investigated the LRG1 expression pattern in coronary artery samples." (PMID 34291056, 2021). "The association suggests that LRG1 participates in the progression of atherosclerosis by inducing inflammation." (PMID 32249825, 2020). "During atherosclerosis LRG1 induces M1 polarization by activating ERK1/2 and JNK pathways exacerbating plaque inflammation." (PMID 41459510, 2025). "LRG1 induces M1 macrophage polarization via the ERK/JNK pathway, and its deficiency significantly attenuates atherosclerosis progression." (PMID 41459510, 2025). "Using apolipoprotein E knockout mice (ApoE-/-) (fed with Western diet) that developed advanced atherosclerosis and using human carotid endarterectomy, we showed that LRG1 accumulated into an atherosclerotic plaque, preferentially in calcified areas." (PMID 38003727, 2023). "In conclusion, our results identified for the first time that LRG1 is a direct contributor to vascular calcification and suggest a role of this molecule in the development of plaque complications in patients with atherosclerosis." (PMID 38003727, 2023). "This suggests a potential mechanistic link between LRG1, inflammation and atherosclerosis in this patient population, and broadens the role of LRG1 in diseases characterized by chronic inflammation." (PMID 32249825, 2020). "Furthermore, in a recent study employing the Western diet apolipoprotein E knockout (ApoE−/−) mouse model of atherosclerosis, LRG1 was detected within the atherosclerotic plaque, particularly in calcified regions." (PMID 38745756, 2024). "Upregulation of LRG1 expression in diseases like atherosclerosis might have an important role in modulating endothelial activation." (PMID 34291056, 2021). "As atherosclerosis is the principal cause of most critical limb ischemia (CLI), we evaluated circulating LRG1 levels in CLI patients and demonstrated a positive correlation between LRG1 and soluble TNFR1 in CLI." (PMID 34291056, 2021).
gastric cancer (8 papers, 2015 to 2024). A primary or metastatic malignant neoplasm involving the stomach. "In patients with gastric cancer, elevated LRG-1 levels positively correlate with local tumor tissue angiogenesis and tumor cell-conditioned medium promotes migration, as well as tube formation of endothelial cells in vitro." (PMID 38413424, 2024). "Serum LRG1 of gastric cancer patients was significantly higher than that of healthy volunteers, and increased with the progression of gastric cancer pathological stage." (PMID 35095520, 2021). "LRG-1 expression (serum or immunohistochemical staining) in patients with gastric cancer was higher than that in healthy controls, and LRG-1 expression increased with the progression of the pathological stage." (PMID 30760292, 2019). "The NEAT1/miR-130/IRF1 axis in gastric cancer, NEAT1/miR-24-3p/LRG1 axis in thoracic aortic aneurysm, NEAT1/miR-324-5p/RAN axis in retinoblastoma and NEAT1/miR-497-5p/PIK3R1 axis in renal tubular oxidative injury have been widely studied." (PMID 39546499, 2024). "Moreover, other proteins revealed in both reports included upregulated A2GL (LRG1), ITIH3, ORM2 and SHGB, which collectively indicated very high conformity of serum proteome signature of gastric cancer that based on samples of unrelated Polish and India’s populations." (PMID 26376850, 2015).
lung fibrosis (8 papers, 2017 to 2023). "CD14 and LBP are mediators of lung inflammation that are produced in response to infectious processes and LRG1 is a hallmark of risk for lung fibrosis assessment." (PMID 35884998, 2022). "As for the associations with Ssc clinical features, LRG1 proved to be a good biomarker for pulmonary fibrosis, while MZB1 proved to be a good biomarker for extensive skin fibrosis." (PMID 36277429, 2022). "LRG1 has also been identified as a promoter of lung fibrosis through the modulation of TGF-β-induced SMAD2 phosphorylation and the activation of profibrotic responses in fibroblasts." (PMID 37569820, 2023). "LRG1 seems a good biomarker for pulmonary fibrosis, while MZB1 is a good biomarker for extensive skin fibrosis." (PMID 36277429, 2022). "Additionally, Lrg1 promotes lung fibrosis following bleomycin treatment by influencing Tgfβ signaling in fibroblasts." (PMID 37932771, 2023). "Strikingly, Lrg1 ko mice are protected from lung fibrosis when given the same treatment." (PMID 37932771, 2023). "Patients with pulmonary fibrosis expressed higher LRG1 and MZB1 concentrations." (PMID 36277429, 2022). "Patients with pulmonary fibrosis had higher LRG1 concentrations compared to patients without pulmonary fibrosis (46.37 ng/mL (24.84) vs 30.27 ng/mL (15.79), P = 0.002)." (PMID 36277429, 2022).
myocardial infarction (8 papers, 2020 to 2025). Gross necrosis of the myocardium, as a result of interruption of the blood supply to the area, as in coronary thrombosis. "On the contrary, it is reported that LRG1 is an inhibitor for adverse cardiac remodeling, and its deficiency aggravates myocardial fibrosis with cardiac dysfunction after myocardial infarction." (PMID 38742172, 2024). "In a mouse model of myocardial infarction, cardiac LRG1 levels significantly increased during the acute inflammatory response before gradually declining as tissue remodelling progressed towards the fibroproliferative phase." (PMID 35062948, 2022). "Alternatively, following myocardial infarction, miR-494-driven Lrg1 suppression downregulates the Wnt/β-catenin signalling pathway ultimately promoting cell migration and tissue remodeling, which are key for the restoration of organ functionality." (PMID 35062948, 2022). "Predictive molecules of LRG1 and miRNAs engaged in pathological development of stable coronary artery disease progressing to acute myocardial infarction." (PMID 35095520, 2021). "In mice, LRG1 has a protective function against adverse cardiac remodeling in experimentally induced myocardial infarction." (PMID 32395893, 2020). "In keeping with our data, the expression of Lrg1 was highest at 1 day after myocardial infarction and gradually decreased from 4 to 14 days, indicating that Lrg1 may serve as a potential early predictor of cardiovascular diseases such as septic cardiomyopathy." (PMID 35721566, 2022). "Indeed, there is growing evidence to support the functional relevance of LRG1 as a biomarker for early onset myocardial infarction." (PMID 33779078, 2021). "In terms of mechanism research, overexpressed miR-494 bound with LRG1 inactivated Wnt signaling pathway might promote fibroblasts and vascular endothelial cells proliferation in myocardial infarction." (PMID 35095520, 2021). "Indeed, in mouse models of myocardial infarction, LRG1 ablation results in aggravated myocardial fibrosis and heart dysfunction after infarction." (PMID 32249825, 2020). "In support of this hypothesis, LRG1 circulating levels were shown to be predictive of early atherosclerotic events but not of late-stage myocardial infarction." (PMID 35062948, 2022).
prostate carcinoma (7 papers, 2010 to 2024). A carcinoma that arises from epithelial cells of the prostate gland. "LRG1 biomarker is associated with I-O proteins and can be used to improve stratification and monitoring of prostate cancer patients undergoing ADT + RT." (PMID 38386171, 2024). "LRG1 has previously been implicated as a promising biomarker for aggressive prostate cancer in an animal model." (PMID 36500247, 2022). "Though emerging studies have reported LRG1 associated with unfavorable outcomes in multiple cancer types, including prostate cancer, the function of LRG1 is so far largely unknown." (PMID 36500247, 2022). "IHC examination showed that LRG1 protein was significantly upregulated in advanced prostate cancer and functional assay revealed that ectopic expression of LRG1 can significantly enhance the malignant phenotype of prostate cancer cells." (PMID 36681849, 2023). "Several proteomic studies based on serum samples have found LRG1 to be elevated in more aggressive prostate cancer." (PMID 36500247, 2022). "However, if LRG1 plays a role in prostate cancer distant metastasis and the machemism of LRG1 induced angiogenesis needs further study." (PMID 36681849, 2023). "Immunohistochemistry of tissue microarray showed that LRG1 protein was significantly upregulated in advanced prostate cancer and functional assay revealed that ectopic expression of LRG1 can significantly enhance the malignant phenotype of prostate cancer cells." (PMID 36681849, 2023). "Results showed that LRG1-overexpressed cell derived exosomes promoted tube formation of HUVEC cells than that from control cells, indicating that exosomal LRG1 protein may be involved in the process of PCa angiogenesis, which facilitate the distant metastasis of advanced prostate cancer." (PMID 36681849, 2023). "Due to the role of exosome-derived LRG1 protein in prostate cancer angiogenesis is unknown." (PMID 36681849, 2023). "However, whether the exosomal LRG1 derived from prostate cancer cells and the functional role of LRG1 protein in prostate cancer is far from known." (PMID 36681849, 2023). "Finally, the functional role of exosomal protein LRG1 was studied in prostate cancer." (PMID 36681849, 2023). "The clustering yielded a clear pattern of the five upregulated EV proteins (i.e., SERPINA3, SCGB3A1, LRG1, SERPINA6, and CP) enriched in the prostate cancer cases." (PMID 36500247, 2022). "We assessed the levels of urinary EV-associated proteins based on 40 samples consisting of 20 cases and 20 controls, where 18 EV proteins were identified to be differentiated in prostate cancer outcome, of which three (i.e., SERPINA3, LRG1, and SCGB3A1) were shown to be consistently upregulated." (PMID 36500247, 2022). "We observed several EV proteins, particularly SERPINA3, LRG1, and SCGB3A1, which showed a consistent difference between prostate cancer cases and non-prostate cancer controls across three DIA methods, which could be suggested as potential biomarkers and deserve further verification." (PMID 36500247, 2022). "In comparison to the discovery cohort, the identified EV proteins (i.e., SERPINA3, LRG1, and SCGB3A1) gained from the validation cohort clearly complied with the discovery cohort, which indicated the effect of the identified EV proteins on prostate cancer were stable." (PMID 36500247, 2022).
Cerebral ischemia (6 papers, 2023 to 2025). Restriction of arterial blood supply to the brain associated with insufficient oxygenation to support the metabolic requirements of the tissue. "A recent study demonstrated that Lrg1 upregulation is associated with increased brain infarct volume, neuronal apoptosis, and enhanced autophagy, exacerbating cerebral ischemia‒reperfusion injury." (PMID 38037097, 2023). "Researchers have shown that Lrg1 is associated with increased brain infarct volume, brain cell apoptosis, and enhanced autophagy, aggravating cerebral ischemia reperfusion injury." (PMID 38037097, 2023). "Leucine-rich alpha-2 glycoprotein 1 (Lrg1) appears to be associated with the progression of cerebral ischemia‒reperfusion injury, but the exact mechanism of it is unknown." (PMID 38037097, 2023). "However, the precise role and underlying mechanisms of Lrg1 in the process of cerebral ischemia‒reperfusion injury remain elusive." (PMID 38037097, 2023). "Another study on cerebral ischemia–reperfusion injury highlights the role of Leucine‐rich alpha‐2 glycoprotein 1 (Lrg1) in modulating various cellular components, including the blood–brain barrier (BBB) and microglia, in a model of focal cerebral ischemia." (PMID 39834143, 2025). "Following cerebral ischemia–reperfusion injury, LRG1 is recognized as a potential signaling molecule." (PMID 39391051, 2024). "In this study, we employed Lrg1 knockout mice to investigate the role of Lrg1 in cerebral ischemia‒reperfusion injury." (PMID 38037097, 2023). "Wild-type (WT) and Lrg1 knockout (Lrg1−/−) mice were used to investigate the role of Lrg1 after cerebral ischemia‒reperfusion injury." (PMID 38037097, 2023). "In summary, our investigation has elucidated how Lrg1 modulates the process of cerebral ischemia‒reperfusion injury by altering the functional states of multiple cellular components of the brain." (PMID 38037097, 2023). "Here, we used scRNA‒seq to analyze the effects of Lrg1 knockout on the functional state of microglial cells following cerebral ischemia‒reperfusion injury." (PMID 38037097, 2023). "Lrg1 expression was increased in various cell types of brain tissue after cerebral ischemia‒reperfusion injury." (PMID 38037097, 2023). "The findings presented herein suggest that Lrg1 knockout attenuate the disruption of the BBB following cerebral ischemia‒reperfusion injury in cerebral tissue." (PMID 38037097, 2023). "Lrg1 knockout reduced cerebral edema and infarct size and improved neurological function after cerebral ischemia‒reperfusion injury." (PMID 38037097, 2023). "To validate the role of Lrg1 as a target in cerebral ischemia‒reperfusion injury, we compared the cerebral infarct volume, water content, and neurological deficits of Lrg1−/− mice and WT mice after MCAO/R." (PMID 38037097, 2023). "Single-cell RNA sequencing analysis of WT and Lrg1−/− mouse brain tissues after cerebral ischemia‒reperfusion injury revealed that Lrg1 knockout enhances blood‒brain barrier (BBB) by upregulating claudin 11, integrin β5, protocadherin 9, and annexin A2." (PMID 38037097, 2023). "Our study demonstrates that Lrg1 knockout effectively protects brain tissue from cerebral ischemia‒reperfusion injury." (PMID 38037097, 2023). "Here, this research indicates that Lrg1 is upregulated in multiple cell types during cerebral ischemia‒reperfusion injury, suggesting its involvement in disease progression across various cellular components." (PMID 38037097, 2023). "Our findings suggest Lrg1 as a promising therapeutic target for cerebral ischemia‒reperfusion injury; however, further experimentation and efforts are needed to refine our understanding of its precise mechanisms in this process." (PMID 38037097, 2023). "Our findings show that Lrg1 knockout reduce cell junction damage in the BBB after cerebral ischemia‒reperfusion injury and promotes the transition of microglia from a proinflammatory state to a tissue repair‒promoting role." (PMID 38037097, 2023).
Cerebral ischemia (continued). "Western blotting was applied to examine the change in Lrg1 expression in the brain during cerebral ischemia‒reperfusion injury." (PMID 38037097, 2023). "In summary, our findings demonstrate that Lrg1 knockout confers protection to brain tissue after cerebral ischemia‒reperfusion injury." (PMID 38037097, 2023). "We observed that knockout of Lrg1 led to significant reductions in cerebral infarct volume, cerebral edema, and neurological deficits after cerebral ischemia‒reperfusion injury." (PMID 38037097, 2023). "Lrg1 is considered a signaling molecule that is potentially induced after cerebral ischemia‒reperfusion injury." (PMID 38037097, 2023). "Utilizing various techniques, such as scRNA-seq, immunofluorescence, and BBB permeability assays, we revealed continuous upregulation of Lrg1 expression across various cell components of the brain in the pathologic process of cerebral ischemia‒reperfusion injury." (PMID 38037097, 2023). "Furthermore, we have demonstrated experimentally that Lrg1 knockout helps to attenuate cerebral ischemia‒reperfusion injury." (PMID 38037097, 2023). "Our results has shown that Lrg1 mediates numerous pathological processes involved in cerebral ischemia‒reperfusion injury by altering the functional states of various cell types, thereby rendering it a promising therapeutic target for cerebral ischemia‒reperfusion injury." (PMID 38037097, 2023). "Based on our observations, we found that Lrg1 knockout could ameliorate brain edema after cerebral ischemia‒reperfusion injury." (PMID 38037097, 2023). "Based on our previous results, we found that Lrg1 knockout could affect the state of microglia and various metabolic pathways in the cerebral ischemia‒reperfusion injury process." (PMID 38037097, 2023). "Specifically, it remains unclear whether the effect of Lrg1 on cerebral ischemia‒reperfusion injury progression is related to various cellular components in brain tissue." (PMID 38037097, 2023). "Compared to WT mice, Lrg1−/− mice exhibited increased protein levels of cell adhesion-related molecules, including Cldn11, Anxa2, Pcdh9, and Itgb5, in endothelial cells after cerebral ischemia‒reperfusion injury." (PMID 38037097, 2023). "Thus, more experiments are needed to further explore the influence of Lrg1 on cerebral ischemia‒reperfusion injury." (PMID 38037097, 2023). "Furthermore, we investigated the changes in various cell types in brain tissue after cerebral ischemia‒reperfusion injury following Lrg1 knockout to elucidate the role of Lrg1 in cerebral ischemia‒reperfusion injury." (PMID 38037097, 2023). "Similarly, increased LRG1 was found in brain endothelial cells in a rat brain ischemia model with expression correlating positively with VEGF, Ang2 and TGF-β, indicating a protective role for LRG1 by promoting de novo formation of blood vessels, possibly through TGF-β." (PMID 38745756, 2024). "Therefore, the protective effect of Lrg1 knockout in cerebral ischemia‒reperfusion injury may be due to alterations in the microglial functional state." (PMID 38037097, 2023). "Moreover, our results suggest that Lrg1 knockout may alleviate oligodendrocyte apoptosis after cerebral ischemia‒reperfusion injury." (PMID 38037097, 2023). "However, it remains unclear in which specific cells Lrg1 expression is elevated after cerebral ischemia‒reperfusion injury." (PMID 38037097, 2023). "Multiple cell types showed high Lrg1 expression levels in the brains of mice with cerebral ischemia‒reperfusion injury, suggesting that the protective effect of Lrg1 knockout on brain tissue after cerebral ischemia‒reperfusion injury may result from its action on multiple cell types." (PMID 38037097, 2023). "To the best of our knowledge, we are the first to report that Lrg1 knockout can block the leakage of the BBB, promoting BBB integrity after cerebral ischemia‒reperfusion injury." (PMID 38037097, 2023).
Cerebral ischemia (continued). "We believe that Lrg1 knockout may regulate the expression of critical junction molecules, such as Cldn11 and Anxa2, affecting their protein expression and ultimately preserving BBB stability after cerebral ischemia‒reperfusion injury and reducing brain edema." (PMID 38037097, 2023).